RN7SL429P (RNA, 7SL, cytoplasmic 429, pseudogene)
Gene: Miscellaneous RNA gene on chromosome 15 (74,072,454 to 74,072,676, reverse strand). Ensembl gene ENSG00000278604.
Homologues: Orthologues: macaque Metazoa_SRP (75% identical), macaque Metazoa_SRP (48% identical), macaque Metazoa_SRP (47% identical), macaque Metazoa_SRP (46% identical), macaque Metazoa_SRP (45% identical), macaque Metazoa_SRP (43% identical), macaque Metazoa_SRP (34% identical), macaque Metazoa_SRP (33% identical), macaque Metazoa_SRP (32% identical), macaque Metazoa_SRP (19% identical), macaque Metazoa_SRP (18% identical), macaque Metazoa_SRP (17% identical), and 2 more. Paralogues in human: RN7SL327P (100% identical), RN7SL489P (100% identical), RN7SL853P (100% identical), RN7SL241P (86% identical), RN7SL214P (83% identical), RN7SL417P (79% identical), RN7SL319P (78% identical), RN7SL469P (76% identical), RN7SL673P (76% identical), RN7SL495P (76% identical), RN7SL628P (76% identical), RN7SL719P (76% identical), and 709 more.